CD44 (CD44 molecule (IN blood group))
Diseases named in the same sentence as CD44 in open-access papers (continued):
Sharing a sentence is not in itself a finding about the gene and the disease.
breast carcinoma (continued). "Furthermore, NF-κB inhibition and subsequent CD44 repression decreases cell proliferation and invasiveness of breast cancer cells." (PMID 25184276, 2014). "We show for the first time that manipulation of CD44 raft affiliation via site-directed mutagenesis of palmitoylation sites influences the migration of invasive breast cancer cells, and is sufficient to induce a motile phenotype and functions in non-invasive cells." (PMID 24512624, 2014). "However, the oncogenic mechanism(s) occurring during HA-activated and CD44-specific breast cancer progression remain(s) to be determined." (PMID 24606718, 2014). "Furthermore, the interaction between CD44 and hyaluronan determines the adhesion of breast cancer cells." (PMID 24614402, 2014). "The initial stem cell markers of breast cancer are defined as CD44+/CD24−/low." (PMID 23990015, 2014). "Another cell surface marker is the single-chain sialoglycoprotein CD24, which is associated with cancer stem cell characteristics in colorectal and pancreatic cancer, while head and neck cancer cells and breast cancer cells with CD44+CD24−/low expression are highly tumorigenic." (PMID 24122205, 2014). "Our results support a novel mechanism whereby CD44 palmitoylation and consequent lipid raft affiliation inversely regulate breast cancer cell migration, and may act as a new therapeutic target in breast cancer metastasis." (PMID 24512624, 2014). "The data used in this case study for evaluation and validation comes primarily from a study that profiled and compared normal breast epithelium tissue obtained from reduction mammoplasties and highly tumorigenic breast cancer cells isolated from tumors (ESA+ CD44+ CD24-/low Lin-)." (PMID 24650281, 2014). "Finally CD44 palmitoylation status and lipid raft affiliation was assessed in primary cultures from a small panel of breast cancer patients." (PMID 24512624, 2014). "However, cancer initiating cells in other neoplasms have been characterized by at least 2 different surface markers; CD44+/CD24-/lin- in breast cancer, a2b5+/CD133- in glioblastoma and CD34+/CD38− in leukemia:." (PMID 25105565, 2014). "In the case study presented in this section we attempt to compare the various biological contexts that emerge when examining differentially expressed genes identified from mRNA profiling of CD44+ CD24-/low breast cancer cells as compared with normal breast epithelium tissue." (PMID 24650281, 2014). "A similar approach was recently used to deliver docetaxel to CD44 + breast cancer." (PMID 24642908, 2014). "Remarkably, breast cancer cells expressing CD44 displayed varying levels of toxin resistance." (PMID 24990559, 2014). "CD44 can exist in a variety of isoforms due to alternative splicing, and EMT has been associated with a switch from the variant isoform (CD44v) to the standard isoform (CD44s) during breast cancer progression." (PMID 24498388, 2014). "Given the fact that exon v10 is in the ectodomain of CD44, we hypothesized that CD44 forms a molecular complex with other cell surface molecules through exon v10 in order to promote migration of breast cancer cells." (PMID 24586375, 2014). "In addition to breast cancer, CD44 was considered to be a CSL-cell marker in ovarian, prostate and pancreatic cancer, and head and neck squamous cell carcinoma." (PMID 24765178, 2014). "Therefore, the development of small molecules (i.e. DNA aptamer) that specifically recognize and antagonize the biological functions of exon v10 of CD44 would be a promising approach for treatment of TN breast cancer patients." (PMID 24586375, 2014). "We investigated in particular whether Alu and LINE-1 hypomethylation is distinct in relation to breast cancer subtype and breast cancer stem cell phenotypes as represented by CD44+/CD24− and ALDH1 expression." (PMID 24971511, 2014). "Cancer cells with up-regulated CD44 expression are responsible for metastasis in breast cancer." (PMID 25184276, 2014).
breast carcinoma (continued). "In breast carcinoma, the CSCs have been identified as a CD44+/CD24− cell population." (PMID 25472619, 2014). "CD44 has previously been shown to play a role in migration and invasiveness of breast cancer cells." (PMID 25184276, 2014). "Likewise, Retinoic acid receptor alpha, CD44 and deltaEF1 had been reported to be involved in the development of tamoxifen resistance in breast cancer." (PMID 24622579, 2014). "In addition, transcription factors known as tumor suppressors or genes related to breast cancer including c-FOS, EGR1, ID2 and SERPINB2, as well as suppression of metastasis associated genes (CD44 and IL11) have emerged as molecular targets of BSP knockdown." (PMID 24980816, 2014). "Thus, hyaluronan binding to CD44 affects the adhesiveness of breast cancer cells to microvascular endothelial cells." (PMID 24614402, 2014). "Another possible scenario is that Regimen 2 treated patients might present a higher population of breast cancer stem cells (BCSCs) identified by the cell-surface markers CD44+/CD24−/low which demonstrate chemo- and radiotherapy resistance." (PMID 24632568, 2014). "While CD44 promotes iota cytotoxicity in non-breast cancer cells, our data is the first to illustrate that CD44 may actually confer resistance to iota toxin in breast cancer." (PMID 24990559, 2014). "The published links between CD44WT overexpression and cell migration/invasion in breast cancer cell lines and patient samples may thus also reflect a proportional decrease in CD44 palmitoylation status." (PMID 24512624, 2014). "Furthermore, we demonstrate temporal reductions in palmitoylated CD44 during stimulated migration of breast cancer cells." (PMID 24512624, 2014). "Thus, identifying the precise mechanisms of interaction between iota toxin with LSR and CD44 is a necessary step towards developing targeted therapies for breast cancer." (PMID 24990559, 2014). "Many groups have enriched for functional breast cancer stem cells using ESA+/CD44+/CD24−/low." (PMID 24583601, 2014). "Recent studies suggest that breast cancer cells express various CD44 isoforms." (PMID 24586375, 2014). "This supports the hypothesis that CD44 expression in breast cancer cells may provide resistance to iota toxin." (PMID 24990559, 2014). "This CD44 isoform acts as a mediator of HA-promoted motility in breast cancer cell lines." (PMID 24083250, 2013). "Therefore, CD44 has been recognized as one of the key cell surface biomarkers for cancer stem cells in breast cancer." (PMID 24386318, 2013). "Breast cancer stem cells have also been reported to express the phenotype CD44+/CD24−." (PMID 24376586, 2013). "In addition, we defined the molecular cross-talk between STAT3, hTERT and CD44 signaling pathways in aggressive breast cancer cells." (PMID 24386318, 2013). "Our findings are in agreement with the concept that genetic variations in CD44 gene may possibly effect the altered binding of its ligand- hyaluronan which leads to increased breast cancer cell growth and differentiation." (PMID 23940692, 2013). "Furthermore, a novel STAT3 inhibitor, LLL12, suppresses ALDH+ and ALDH+/CD44+/CD24− subpopulations of breast cancer cells in vitro and inhibits tumor growth in mouse xenograft and mammary fat pad models in vivo." (PMID 24376586, 2013). "Therefore, finding the optimal HA density on MNCs is needed for the most effective diagnosis and treatment for CD44-overexpressed breast cancer." (PMID 23547716, 2013). "CD44 gene polymorphisms have not been widely studied with only few reports in breast cancer worldwide." (PMID 23940692, 2013). "The ability of vitamin D to suppress CD44 expression in breast cancer cells may suggest that manipulation of vitamin D levels may reduce tumor burden." (PMID 23341935, 2013). "In human breast cancer, it has been shown that breast CSCs have a CD44+/CD24- phenotype." (PMID 23799994, 2013).
breast carcinoma (continued). "Noteably, CD44(+)/CD24(-/low) breast cancer stem-like cells are associated with tumor recurrence and play a pivotal role in the clinical behavior of triple-negative breast cancer, a particularly therapy-resistant subclass of breast cancer." (PMID 24392029, 2013). "Also, in samples of pleural or ascites effusions of breast cancer patients the miR-200 family members were consistently down-regulated in CD44+CD24−/low putative BCSCs." (PMID 23860207, 2013). "In addition, all seven of the normal adjacent tissues from women with ER+ breast cancer that were positive for CD44+CD49f+CD133/2+ also exhibited high tumorigenic signature patterns." (PMID 24008095, 2013). "Secreted serglycin may interact with CD44 on breast cancer cell membrane and trigger CD44 signaling promoting cancer cell migration and invasion." (PMID 24205138, 2013). "Furthermore, breast cancer cells with the overlapping profile ALDH+/CD44+/CD24− are more enriched in tumor initiating cells than each of these markers alone." (PMID 24376586, 2013). "Similarly, two mRNA transcripts were recently shown to act as miRNA sponges: the 3' UTR regions of Versican (VCAN) mRNA in hepatocellular carcinoma (HCC) and of CD44 mRNA in breast cancer cells." (PMID 24216986, 2013). "Further, it was found that CD44+/CD24-/low breast cancer cells exhibit epithelial-to-mesenchymal transition (EMT) features that might be responsible for their aggressive clinical behaviour." (PMID 24229464, 2013). "Based on the work presented here, we think that treatment targeting CD44 with antibody or other approaches has the potential to become important therapy for invasive and metastatic basal-like carcinomas, and perhaps other subsets of breast carcinomas." (PMID 24324613, 2013). "Similarly, CD44 mRNA is elevated in breast cancer cells and its 3' UTR harbors binding sites for miR-328, miR-512-3p, miR-491 and miR671." (PMID 24216986, 2013). "Therefore, identification of interacting molecules in a cell-type specific manner is important to understand the biological role of CD44 in human breast cancer." (PMID 23326564, 2013). "Thus, our data suggest that the synergistic efficacy of co-treatment with sorafenib and radiation resulted in a potential combined treatment effect for specific targeting of CD44+CD24−/low cells from breast cancer cells in vitro." (PMID 23314174, 2013). "However, altered binding of hyaluronan to CD44 can activate cell growth, survival, invasion and metastasis in breast cancer as well as in other cancers." (PMID 23940692, 2013). "Notably, it was demonstrated that CD44 positive breast cancer stem cells had preferential activation of STAT3, suggesting STAT3 as a potential therapeutic target for human breast tumors." (PMID 24386318, 2013). "In addition, they demonstrated that YB-1 is involved in tumor initiating surface marker expression, including CD44 in breast cancer initiating cells." (PMID 24044901, 2013). "Interestingly, a recent report showed that POSTN is expressed higher in the sorted human CD44+/CD24−/line− breast cancer stem cells compared to the control cells and the levels of POSTN are related to the CSC ratio in human breast cancer specimens." (PMID 24009721, 2013). "Also among DTC detected in the bone marrow of early breast cancer patients, 72% expressed the putative stem cell phenotype, CD44+CD24−." (PMID 24305653, 2013). "A recent study demonstrated significantly elevated expression of uPA in highly invasive basal-like breast cancer in a CD44-dependent manner, and a protein microarray study of primary breast cancer tissue found significant correlation between expression levels of uPA and STAT3." (PMID 23326564, 2013).
breast carcinoma (continued). "Furthermore, we systemically analyzed the ultrasturcture, invasion capacity, and tumor formation in breast cancer MCF7 cells with different CD44/CD24 genotypes." (PMID 23799994, 2013). "We found that the CD44+/CD24-/low breast cancer cells showed numerous protrusions on the cell surface and had many microvilli and pseudopodia, indicating such ultrastructures may contribute to higher tumorigenesis and invasion ability." (PMID 23799994, 2013). "More specifically, a novel animal model of breast cancer metastasizing to bone has been investigated which consisted of injecting human CD44+/CD24−/low BCSCs subpopulation from MDA-MB-231 cells in mice previously implanted with human bone in the right or left dorsal flanks." (PMID 23301832, 2013). "In addition to the therapeutic resistance, CSCs have been reported to exhibit specific surface markers such as CD44+/CD24− in breast cancer." (PMID 23799116, 2013). "Breast cancer cells with a CD44+/CD24low/- surface phenotype were found to have tumor-initiating properties with stem-cell like features and invasive ability, however it is unclear whether their presence in a tumor has clinical implications." (PMID 24124614, 2013). "Their relationship to disseminated tumour cells (DTCs) in tissues is unclear, although a recent publication showed that the presence of CD44+CD24-/lo cells (putative CSCs) in the bone marrow is an independent adverse prognostic indicator in patients with early stage breast cancer." (PMID 24286369, 2013). "Tumour-associated changes such as the Tn antigen and other changes in O-glycosylation have been found to be immunogenic and present on a variety of proteins, e.g. CD43 in T-cell leukaemia cells, MUC-1 in colon cancer, CD44 in breast carcinoma and nucleolin in melanoma." (PMID 23637900, 2013). "Our study suggests that repression of STAT3 signaling by targeting CD44 may be a key molecular mechanism of BXL0124-induced inhibition of breast cancer invasion, a critical step in cancer progression." (PMID 23326564, 2013). "Moreover, a positive correlation exists between the expression levels of IL-1alpha, IL-6, IL-8 and the CD44(+)/CD24(-/low) population in breast cancer cell lines." (PMID 24392029, 2013). "Transplantation experiments using immunocomprimised mice, showed that as few as 100 human breast cancer cells with the cell surface markers CD44+CD24−/low were tumorigenic and could be serially passaged to generate new tumours." (PMID 23861811, 2013). "Using flow cytometry, CSCs were detected in canine mammary tumors as cells CD44+ and CD24-." (PMID 24119896, 2013). "Specifically, only 200 CD44+/CD24-/low/ESA+/lin- breast cancer cells, isolated from patient primary tumors, could regenerate and expand to form secondary tumors that also contained CSCs, in as little as 12 weeks in mice." (PMID 22934288, 2012). "Associations between breast cancer susceptibility and CD44 polymorphisms have not been detected in any population using case-control studies." (PMID 22788972, 2012). "Since CD44 is also a breast cancer stem cell marker, our data suggest that, in vivo, hypoxic tumor regions may contain cell populations enriched with this marker." (PMID 22937154, 2012). "That suppression of CD44 is able to deplete heregulin-induced activation of erbB signalling and also depletes HA-promoted erbB2:erbB3 association suggest a potential value of therapeutically targeting CD44 in breast cancer, potentially to improve the effect of current targeted therapies." (PMID 23039365, 2012). "In addition, the percentage of CD44+/CD24− breast cancer cells is higher in the primary tumours of patients with shorter metastatic-free survival, therefore representing an independent predictor of metastasis development." (PMID 23028444, 2012). "Notably, it has been shown that stem-like cells isolated from human breast cancer co-express high levels of CD44 and high levels of mesenchymal markers, including Slug." (PMID 22493711, 2012).
breast carcinoma (continued). "Furthermore, differences in the number of detectable human breast cancer cells in CD44-enriched versus CD44-depleted chimeras indicates that our detection of human cells by keratin expression is human-specific, with no cross-reactivity to mouse." (PMID 23155468, 2012). "In a review of existing literature on the role of CD44/CD24 in recurrent human cancer, investigators showed positive associations between CD44+/CD24- and prognosis, especially in breast cancer; and the CD44+/CD24- phenotype of breast cancer cells was also associated with invasive properties." (PMID 22839505, 2012). "The aim of our study was to identify the CD44+/CD24− cell population in surgical specimens of primary breast carcinomas using immunohistochemical methods, with the goal of correlating the amount and distribution of CD44+/CD24− cells with clinicopathological features." (PMID 23028444, 2012). "These two indicators for LN metastasis of breast cancer markers may only relate to the distribution of organs, while CD44+CD24-/low cells not only relate to the distribution of organs, but also to their biological characteristics (invasiveness)." (PMID 23046710, 2012). "Finally, miR-373 was also shown to be upregulated while CD44 was decreased in metastatic breast cancer tissue specimens, which additionally implicate these miRNAs for their roles in breast cancer metastasis." (PMID 23202960, 2012). "The objective of our study was to increase our understanding of CD44-promoted breast cancer cell invasion by defining the effect of CD44 signaling on protease gene expression and activity, and defining the role of these proteases in underpinning HA-induced invasion." (PMID 22621373, 2012). "CD44+CD24-/low breast cancer stem cells might help clinicians to determine the presence of LN metastases." (PMID 23046710, 2012). "In addition, cycling hypoxia has been shown to increase the CD44+/CD24− population in a metastatic breast cancer cell line." (PMID 22937154, 2012). "The objective of the present study was to examine whether the fusion of TAMs and breast cancer cells results in the genetic reprogramming and generation of CD44+CD24−/low breast cancer stem cells (BCSCs), which may contribute to metastasis and relapse." (PMID 22848668, 2012). "Taken together, these data suggest that CD44 may represent a novel point for intervention to suppress progression of endocrine-resistant breast cancer." (PMID 23039365, 2012). "Interaction of hyaluronan and CD44 can promote breast cancer cell adhesion and inhibited invasion." (PMID 22788972, 2012). "In this regard, breast cancer epithelial cell lines (specifically including MCF10A cells) have been shown to exhibit heterogeneous staining for CD44, CD24, and epithelial specific markers, which presumably correlates with the heterogeneous VIM staining in the parental control MCF10A cells." (PMID 22761798, 2012). "Our hypothesis was, if CD44+ and Sca1+ cells are involved in metastasis to the lung from primary mammary carcinomas, we should be able to find such cells in the lungs." (PMID 22277639, 2012). "By targeting the factors that result in the overexpression of CD44, we may be able to better treat breast cancer and metastatic tumors." (PMID 23226410, 2012). "The inability to completely eliminate CR1 expression implies other TFs and/or co-factors may be involved in regulating CD44 expression in breast cancer stem-like SUM 159 cells." (PMID 23226410, 2012). "Our in vitro data here suggests that overexpression of CD44s enhances breast cancer cell sensitivity to both erbB ligands and to HA and that subsequent stimulation of CD44-overexpressing cells results in modulation of erbB dimerisation and enhancement of migration." (PMID 23039365, 2012).